CSF1 (colony stimulating factor 1)
Diseases named in the same sentence as CSF1 in open-access papers (continued):
Sharing a sentence is not in itself a finding about the gene and the disease.
tumor (continued). "This promotes CSF1 dependent recruitment of macrophages, lymphocytes, and multinucleated giant cells which ultimately constitute up to 90% of the tumor mass." (PMID 41523664, 2026). "Loss of PIK3IP1 increased lactate production and histone H4K12 lactylation (H4K12la), coinciding with upregulation of PD-L1 and CSF1 and enhanced tumor immunosuppressive features." (PMID 42206447, 2026). "Peripheral blood monocytes can be recruited into the TME and differentiate into TAMs in response to tumor cell–secreted recruitment factors such as CSF1, CCL2, and CXCL12." (PMID 41426206, 2026). "Conversely, genes associated with immune modulation and tumor progression such as IL-1β, inducible nitric oxide synthase (NOS2), cyclooxygenase (COX) 2, vascular endothelial growth factor (VEGF), and colony stimulating factor 1 (CSF-1) were upregulated." (PMID 41939865, 2026). "Tumor-derived CSF-1 (M-CSF) further recruits monocytes and promotes their differentiation into M2-like TAMs." (PMID 41597210, 2026). "In these additional models, the increase in macrophage secretion of VEGF-A in response to tumor cell CSF-1 was again suppressed through addition of CSF-1R inhibitors or blocking antibodies." (PMID 40646332, 2025). "To examine the role of tumor cell secreted CSF-1 in regulating macrophage VEGF-A secretion, we first determined if TMEM doorway macrophages express the CSF-1 receptor (CSF-1R)." (PMID 40646332, 2025). "TAM-derived epidermal growth factor (EGF) drives the formation of elongated tumor cell protrusions that augment invasion, reinforced by a CSF-1/EGF positive feedback loop that markedly amplifies metastatic behavior." (PMID 41058699, 2025). "We observed that the fluorescence intensity of intracellular CSF-1 in TMEM doorway tumor cells was higher in active TMEM doorways compared to inactive TMEM doorways." (PMID 40646332, 2025). "Several therapies, such as granulocyte‐macrophage colony‐stimulating factor (GM‐CSF) and anti‐CSF‐1 antibody, have been used to reprogram the recruited monocytes to differentiate into anti‐tumoral M1 macrophages instead of tumor‐supportive M2 macrophages." (PMID 40400098, 2025). "This reprogramming is mediated by Th2-skewing cytokines (e.g., IL-4, TGF-β1) and tumor-derived growth factors (e.g., CSF1, GM-CSF), fostering a microenvironment that supports tumor growth and metastasis." (PMID 40433363, 2025). "As a result, blocking the CSF1/CSF1R axis changeds macrophage activation from tumor-promoting M2 to tumor-killing M1 phenotype 45." (PMID 40225567, 2025). "In each tumor component, we compared clinicopathological features between the high and low CSF-1 expression groups." (PMID 39488822, 2025). "For example, through CSF-1R signaling, TAM-derived CCL8 enhances tumor cell secretion of colony-stimulating factor 1 (CSF-1), a key factor required for the survival and differentiation of macrophages and dendritic cells." (PMID 41584608, 2025). "During tumor progression, interleukin (IL)-4 and colony stimulating factor 1 (CSF1) induce the polarization of TAM to M2 phenotype." (PMID 41246345, 2025). "We collected the blood from the mice at the time of sacrifice and found the number of CTCs was significantly lower in the mice where tumor cell CSF-1 had been inhibited compared to control mice." (PMID 40646332, 2025). "TRMs participate in organizing the structure of terminal buds and extracellular matrix, and they exert anti-tumor immunity in a CSF1-dependent manner." (PMID 40649751, 2025). "CAFs recruit granulocytes to the TME by producing colony stimulating factor-1 (CSF-1) that promotes tumour growth and metastasis." (PMID 40852716, 2025). "The authors constructed a tumor-bearing animal model of prostate cancer with local irradiation of 15 Gy and found that the expression level of CSF-1 and the recruitment of tumor-infiltrating bone marrow cells were increased." (PMID 40007537, 2025).
tumor (continued). "The positive feedback between tumor cells and TAMs triggered tumor cells to secrete CSF-1, stimulating TAMs to secrete epidermal growth factor (EGF), which also accelerated tumor invasion and metastasis by destroying the matrix 118-120." (PMID 40083710, 2025). "TAMs stimulated by CSF1 secrete additional CSF1 through paracrine signaling between macrophages and tumor cells, and enhance the invasive properties of tumor cells." (PMID 40109347, 2025). "In summary, due to the crucial regulatory role of the CSF-1/CSF-1R signaling pathway in tumor development and fibrotic processes, inhibiting the CSF-1/CSF-1R signaling pathway seems to be a promising strategy for cancer treatment and fibrosis." (PMID 40007537, 2025). "In tumor implantation models, CSF-1 reduction decreases macrophage density and significantly suppresses metastasis." (PMID 41409281, 2025). "CSF-1 is expressed in a variety of cells, such as osteoblasts and various cancer cells, which can be used as a potential tumor marker." (PMID 40007537, 2025). "By releasing its ligand, CSF-1—potentially through tumor-mediated mechanisms—Csf-1R+ monocytes can differentiate into MDSCs, which then acquire immunosuppressive properties." (PMID 40674934, 2025). "When tumor cells proliferate uncontrollably, they secrete a large amount of CSF-1, stimulating the production of a large number of immunosuppressive M2 macrophages." (PMID 40007537, 2025). "For example, Tumor-associated macrophages (TAMs), attracted by tumor-derived chemokines like CCL2 and CSF-1, often adopt an M2-like phenotype, producing anti-inflammatory cytokines like IL-10 and TGF-β." (PMID 40739089, 2025). "In the tumor microenvironment (TME), macrophages are regulated by tumor-derived CSF-1, which binds to CSF-1R and promotes their survival and polarization into tumor-promoting phenotypes." (PMID 41462587, 2025). "Specifically, macrophages secrete epidermal growth factor (EGF), which binds to epidermal growth factor receptors (EGFR) on tumor cells, activating downstream signaling pathways and inducing colony-stimulating factor 1 (CSF-1) secretion." (PMID 40547026, 2025). "Tumor-derived cytokines such as IL-6, IL-8, IL-10, CSF-1, CCL2, CXCL2, PGE2 and TGF-β promote MDSC expansion and recruitment, whereas hypoxia shifts MDSC metabolism toward fatty acid oxidation, reinforcing their immunosuppressive properties." (PMID 40628732, 2025). "Bidirectional signaling between TAMs and tumor cells, such as CSF-1/EGF loops, foster a pro-metastatic niche, while TAM-derived factors like TGF-β and PGE2 enhance cancer stem cell plasticity." (PMID 40422244, 2025). "CSF-1 upregulates Tie2 in TAMs in gastric cancer, linking them to vessel formation and tumor cell intravasation." (PMID 40872551, 2025). "We found that specific inhibition of tumor-derived CSF-1 decreased TMEM doorway activity as dextran extravasation was blocked." (PMID 40646332, 2025). "Immunohistochemical staining for CD163 and CSF-1 was performed, and differences in immunohistochemical results among the three tumor components were analyzed." (PMID 39488822, 2025). "We then visualized and quantified the expression of CSF-1 (red) in TMEM doorway tumor cells of both active and inactive doorways." (PMID 40646332, 2025). "In OC and BC, ALKBH3 enhances the half-life of CSF-1 mRNA by removing m1A from the GC-rich region of the 5 UTR of CSF-1 mRNA, facilitating macrophage recruitment and tumor invasion." (PMID 40406121, 2025). "Through paracrine and autocrine signaling, tumor cells and associated stromal elements often produce high levels of CSF1 or IL-34, activating CSF1R on circulating myeloid precursors and promoting their migration into the tumor." (PMID 40821795, 2025).
tumor (continued). "To examine the effects of blocking tumor-derived CSF-1 on TMEM doorway activity, we stained the tumor tissue for endomucin and TMR-Dextran and measured the amounts of extravascular dextran compared to the vascular area." (PMID 40646332, 2025). "Here we demonstrate that while the TMEM doorway tumor cell and macrophage remain in direct and stable contact on the blood vessel, the CSF-1 signaling persists, resulting in localized macrophage secretion of VEGF-A." (PMID 40646332, 2025). "This shift has been confirmed in several studies using horizontal MPS, where co-culture of tumor cells with macrophages drives stable M2 differentiation via colony-stimulating factor 1 (CSF-1) signaling." (PMID 41123820, 2025). "Since tumor cells are known to secrete CSF-1, we investigated if TMEM doorway tumor cells express CSF-1, and if this expression is associated with TMEM doorway vascular opening." (PMID 40646332, 2025). "Tumour cells, macrophages, and other stromal components secrete CSF1, sustaining TAM viability within the TME." (PMID 40948757, 2025). "Co-localization of vascular tight junction ZO-1 and adherens junction CD31 staining increased with tumor cell CSF-1 blockade, providing further evidence that endothelial junctions were less permeable upon inhibition of CSF-1 signaling." (PMID 40646332, 2025). "We found that TMEM doorway tumor cells secrete CSF-1, which binds to the CSF-1R on TMEM doorway macrophages." (PMID 40646332, 2025). "Functional assays show that SPON2 promotes OS cell proliferation, migration, invasion, and angiogenesis by enhancing the secretion of IL10, CCL2, and CSF1, which leads to M2 macrophage polarization and an immunosuppressive tumor microenvironment." (PMID 40730813, 2025). "Within the TME, tumour-derived CSF1 induces macrophage expression of NKG2D ligands, including MICA/B and ULBPs, thereby promoting NK cell activation." (PMID 40948757, 2025). "Since CSF-1 is upregulated in the tumor cell at active TMEM doorways, and secretion of VEGF-A is known to be regulated by CSF-1 in other cell types, we investigated the signaling interplay between the tumor cell and macrophage at the TMEM doorway." (PMID 40646332, 2025). "CRC cells secreted TIMP1 into the tumor microenvironment, where it induced M2-like macrophage polarization and increased the expression of immunosuppressive mediators such as CSF1 and IRF4." (PMID 41511313, 2025). "This explains, for instance, why CSF-1 knockout mice and those treated with a CSF-1 inhibitor have significantly reduced densities of tumor Lyve-1+ cells and lymphatic vessels." (PMID 40507286, 2025). "Cell communication analysis of the CSF1 signaling network revealed that most CSF-1/IL-34 signals were emitted by tumor cells, which were primarily received by TAMs, while the tumor cells also received autocrine CSF-1/IL-34 signals." (PMID 41365876, 2025). "Elevated CSF-1 played a crucial role in the systemic recruitment of primary myeloid cells to the irradiated tumor." (PMID 40007537, 2025). "These macrophages are attracted to the tumor microenvironment by chemotactic signals, including colony‐stimulating factor‐1 (CSF‐1), VEGF‐A, and chemokine (C‐C motif) ligand 2 (CCL2)." (PMID 40944395, 2025). "Inhibition of CSF-1 with tyrosine kinase inhibitors or antibodies are one strategy to inhibit or deplete the pro-tumor M2 macrophage subset." (PMID 39625569, 2025). "Accumulating evidence showed that, upregulated CSF-1 promotes the infiltration, survival, and metastasis of TAMs expressing CSF-1R in the tumor microenvironments, and blocking the CSF-1/CSF-1R signaling pathway can reduce immunosuppressive TAMs in tumors." (PMID 40007537, 2025). "To determine the impact of inhibition of tumor cell-derived CSF-1 inhibition on the levels of VEGF-A expression in TMEM doorway macrophages in vivo, we stained the tumors for VEGF-A, F4/80 to identify macrophages, and endomucin." (PMID 40646332, 2025).
tumor (continued). "Another approach to prevent TAM infiltration into the tumor microenvironment involves inhibiting the CSF-1–CSF-1R axis, which is vital for TAM differentiation, survival, and recruitment." (PMID 40079009, 2025). "In metastatic contexts, macrophages are often polarized into a M2-like phenotype, characterized by the secretion of IL-10, TGF-β, and colony stimulating factor 1 (CSF-1), which suppress inflammation and enhance tumor progression." (PMID 39940643, 2025). "In cancer, MDSCs expand significantly and accumulate in the TME under the influence of tumor-secreted factors such as CSF1, G-CSF, IL-6, and prostaglandins." (PMID 40821795, 2025). "The elevated expression of xCT is also significantly associated with the overexpression of HIF1α, programmed death ligand 1 (PD-L1), colony-stimulating factor 1 (CSF1), tumour-associated macrophage (TAM) and myeloid-derived suppressor cell (MDSC) infiltration." (PMID 41154605, 2025). "In the microenvironment of HCC, MMP21 enhances macrophage recruitment through CCL14 and promotes M2 polarization of macrophages by increasing expression levels of CSF1, ultimately facilitating tumor metastasis." (PMID 40453088, 2025). "HC contained more M2 macrophages and showed higher CSF-1 score than the other two (EC and TC) tumor components." (PMID 39488822, 2025). "While TAMs drive tumor progression through established pathways such as CSF1‐mediated recruitment or IL‐10‐induced immunosuppression, our discovery of the SRC‐1/STAT1/MMP12 axis revealed a distinct mechanism specific to PNI." (PMID 40985319, 2025). "In fact, the CSF1 response has been found in many BC cases, and TRM reprogramming is associated with higher tumor proliferation rates and tumor grades." (PMID 40649751, 2025). "CSF1R, binding to the ligands CSF-1, promotes the accumulation of TAMs with an immunosuppressive phenotype, mediating tumor progression and therapeutic resistance." (PMID 40404633, 2025). "Further researches are needed to achieve further understanding of the interaction between CSF-1/CSF-1R signaling pathway inhibitors and tumor radiotherapy and fibrosis." (PMID 40007537, 2025). "TAM can be derived from blood monocytes that migrate into the tumour following a variety of chemotactic signals (mainly produced by tumour cells), such as macrophage colony-stimulating factor (M-CSF, CSF-1), CCR2, and VEGF." (PMID 40385641, 2025). "In their study they showed how varying the rate of macrophage extravasation and macrophage chemotactic sensitivity to CSF-1 affect the ability (or inability) of macrophages to eliminate a tumor." (PMID 40464993, 2025). "Acute blockade of CSF-1/CSF-1R signaling decreases macrophage VEGF-A secretion as well as TMEM doorway-associated vascular opening, tumor cell trans-endothelial migration, and dissemination." (PMID 40646332, 2025). "with IgG control antibodies or a human-specific CSF-1 blocking antibody, which has less than 5% blocking activity against mouse-derived CSF-1, ensuring that only signaling from human tumor-derived CSF-1 was inhibited." (PMID 40646332, 2025). "TAMs are recruited by hypoxic conditions, necrosis, and tumor-derived cytokines such as CSF1 and IL-6." (PMID 40872551, 2025). "In vestibular schwannomas, tumor-associated SCs comprise “repair-like” and MHC-II antigen-presenting subpopulations that actively recruit macrophages through CSF1 signaling, mimicking nerve injury repair processes to drive tumor growth." (PMID 40421086, 2025). "CSF1 is secreted by tumor cells and binds to the macrophage-surface CSF1 receptor (CSF1R), which chemotactically converted and polarized macrophages to the M2 phenotype." (PMID 39780291, 2025). "M2-TAMs further secrete chemotactic factors including CCL2, CCL5, and macrophage colony-stimulating factor-1 (CSF-1), thereby contributing to immunosuppression and establishing a supportive niche for tumor angiogenesis, metastasis, and invasion." (PMID 40936918, 2025).
tumor (continued). "Recent preclinical studies targeting CSF-1/CSF-1R have yielded promising results in several tumor models." (PMID 40646332, 2025). "Through RNA sequencing, we focused on CSF1, a cytokine secreted by tumor cells, that is important for promoting macrophage recruitment and polarization." (PMID 39780291, 2025). "The progression, survival, and differentiation of TAMs, which often rely on immunosuppressive properties that contribute to tumor growth and treatment resistance, are facilitated by elevated CSF-1 levels in GBM." (PMID 41098573, 2025). "CSF-1 can significantly enhance the tumor growth, invasion, and metastasis, that is key factor for TNBC development." (PMID 40297849, 2025). "Target suppression of CCR5, CCL5 or CSF1 or both by knockdown of HIF significantly suppresses primary tumor growth and metastasis." (PMID 40676710, 2025). "CSF-1, produced by tumor cells, is known to induce monocytes in the peripheral blood to differentiate into tumor-associated macrophages (TAMs)." (PMID 41463178, 2025). "They promote angiogenesis through the production of vascular endothelial growth factor (VEGF), thereby supplying the tumor with nutrients and oxygen, and they produce colony-stimulating factor 1 (CSF-1) to further recruit and sustain TAMs in the TME." (PMID 40917508, 2025). "According to this study, CSF-1/CSF-1R expression correlated with an advanced stage of disease in young patients and tumor metastasis." (PMID 38254773, 2024). "Consistent with this, in metastatic PDAC, tumor cell-derived CSF1 induces macrophages to produce granulin, a secreted glycoprotein that promotes fibroblast activation and stimulates tumor growth." (PMID 39416792, 2024). "Blocking the CSF-1/CSF-1R signaling axis can convert TAMs from a tumor-promoting phenotype to a tumor-killing phenotype." (PMID 39403370, 2024). "CSF-1R is a tyrosine kinase receptor that, when bound to the ligand CSF-1, promotes the differentiation and expansion of MDSCs into MDSCs and TAMs, in addition to promoting the migration of MDSCs to tumours." (PMID 38475858, 2024). "A variety of inflammatory mediators can induce MDSC expansion and recruitment to the TME, including tumor-derived IL-6, IL-8, IL-10, CSF-1, CCL2, CXCL2, PGE2, and TGF-β." (PMID 38254796, 2024). "TNBC secretes cytokine CSF-1, which binds to the CSF-1 receptor (CSF-1R) on TAMs and stromal cells like mesenchymal stem cells (MSCs) that drive their recruitment to the primary tumor and increase metastasis to the lymph nodes and lungs." (PMID 39409110, 2024). "M2-like macrophages mediate the immune escape of tumor cells through PD-1 and are activated by interleukin (IL)-4, IL-10, IL-13, or colony-stimulating factor 1 (CSF-)." (PMID 39113885, 2024). "For HRP patients, targeting indolent CAFs, targeting M2 macrophages via CSF‐1/CSF‐1R inhibitors, targeting bystander T cells via tumor vaccines, and targeting epithelial cells via HDAC inhibitors." (PMID 39136172, 2024). "Lacnotuzumab (MSC110), a monoclonal antibody against CSF-1, has demonstrated anti-tumor efficacy in combination with spartalizumab in several tumor types, including TNBC, in a phase Ib/II study." (PMID 39409110, 2024). "GAMMs adopt a pro-tumorigenic phenotype influenced by tumor-derived cytokines, including CSF-1, which correlates with increased tumorigenesis and poor prognosis." (PMID 39457693, 2024). "Targeting markers on the surface of these defective APCs such as colony-stimulating factor 1 (CSF1) can impair tumor growth." (PMID 39696625, 2024). "In xenograft NB models, blocking macrophage stimulating factors such as CSF-1 has been demonstrated to prolong the survival of tumor-bearing mice." (PMID 38714539, 2024). "In a steady state, TRMs maintain breast tissue homeostasis and anti-tumor immunity in a CSF-1-dependent manner." (PMID 39104525, 2024).